ARL4C (ARF like GTPase 4C)
Diseases named in the same sentence as ARL4C in open-access papers (continued):
Sharing a sentence is not in itself a finding about the gene and the disease.
cancer (continued). "The present study employed gene co-expression analysis to investigate the association between ARL4C expression and MHC genes, as well as immunostimulatory/suppressive checkpoints, across various cancer types." (PMID 38178862, 2023). "In cancer stromal cells, ARL4C expression was significantly stronger in cases with high-grade TB than in cases with low-grade TB (P = 0.0002)." (PMID 37237373, 2023). "The findings revealed a predominant co-expression of ARL4C with MHC genes in the majority of cancer types, wherein ARL4C exhibited a positive correlation with most MHC genes specifically in KICH, LIHC, PRAD, THCA, and UVM." (PMID 38178862, 2023). "Both are known to be factors that worsen a prognosis, suggesting ARL4C expression in cancer stromal cells is of great prognostic significance." (PMID 37237373, 2023). "In cancer stromal cells, there was weak positive correlation between ARL4C expression and TB grades (r = 0.3526, P = 0.0037)." (PMID 37237373, 2023). "ARL4C expression was significantly higher in cancer stromal cells than in cancer cells (P < 0.0001)." (PMID 37237373, 2023). "In cancer cells, ARL4C expression was significantly stronger in cells with the EMT phenotype compared with those with the non-EMT phenotype (P = 0.0366)." (PMID 37237373, 2023). "In summary, our study extensively investigated the predictive value and immune-related implications of ARL4C in pan-cancer by bioinformatics tools." (PMID 38178862, 2023). "In cancer stromal cells, ARL4C expression were identified near cancer cells and ARL4C expression varied from diffuse to scattered patterns." (PMID 37237373, 2023). "Conversely, ARL4C expression was higher in all other 23 types of cancers compared to normal tissues." (PMID 38178862, 2023). "Within the pan-carcinoma landscape, the expression of ARL4C is highly correlated with immune signaling pathways, as demarcated by the red module." (PMID 38178862, 2023). "This online analysis tool was used to explore the expression of ARL4C in different cancers and its relationship with the clinical characteristics of KIRC patients." (PMID 35774359, 2022). "The differential expression analysis between cancer tissues and their corresponding adjacent normal tissues showed that ARL4C expression in KIRC tissues was higher than that in adjacent kidney tissues." (PMID 35774359, 2022). "After downloading the data of cancer patients from the TCGA database, we used various bioinformatics analysis websites and methods to analyze the expression and function of ARLs and ARL4C." (PMID 35774359, 2022). "Rac is activated as a downstream effector of ARL4C, which reduces the expression of Rho and, in turn, affects the invasion of cancer cells." (PMID 35774359, 2022). "In our study, using a coculture system and cell supernatant, we found that Arl4c expression in cancer cells correlated with PSC activation." (PMID 34849465, 2021). "Arl4c is expressed at high levels in tumors and exerts its oncogenic role in the tumorigenesis, growth, and metastasis of diverse cancers, such as colorectal cancer, lung cancer, and hepatocellular carcinoma." (PMID 34849465, 2021). "High expression of Arl4c in cancer cells promotes paracrine CTGF signaling, resulting in the induction of autophagy flux in PSCs and subsequent activation of PSCs." (PMID 34849465, 2021). "Because aberrant activation of the Wnt–β-catenin and/or EGF–RAS pathways are frequently observed in various types of cancers, ARL4C is indeed expressed in a number of cancers." (PMID 34590580, 2021). "We also discovered some unidentified regulators such as TM9SF3, LYZ, and ARL4C, which are potentially engaged in the cellular transition from the cancer stem cells into metastatic malignant cells." (PMID 34732701, 2021). "In the case of lung and tongue squamous cell carcinoma, it was found that ARL4C promotes proliferation and migration of cells from these types of cancers." (PMID 32426352, 2020).
cancer (continued). "The relationships between ARL4C gene expression and ARL4C DNA methylation in the 3’-UTR was further analyzed using lung SCC cohorts from The Cancer Genome Atlas (TCGA) dataset." (PMID 27835592, 2016). "ARL4C knockdown decreased migration of NCI-H520 and SAS cells, and ARL4C expression rescued the ARL4C-knockdown phenotype of cancer cells, excluding siRNA off target effects." (PMID 27835592, 2016). "ARL4C is also a promising biomarker for the diagnosis of cancer." (PMID 40176913, 2025). "By now, a number of data have already been obtained about ARL4C level regulation in cancer cells." (PMID 39767779, 2024). "ARL4C was highly expressed in cancer cells and cancer stromal cells with the EMT phenotype." (PMID 37237373, 2023). "Furthermore, our analysis revealed that ARL4C expression was significantly higher in 23 out of 33 cancer types examined, suggesting a potential comprehensive role of ARL4C in tumorigenesis." (PMID 38178862, 2023). "In all cases, ARL4C expression was observed in cancer stromal cells and cancer cells." (PMID 37237373, 2023). "ARL4C expression in cancer cells was localized at the invasion front." (PMID 37237373, 2023). "Notably, ARL4C was also expressed in immune cells, and its high expression was found to be correlated with cancer immune activation." (PMID 38178862, 2023). "As a result, it is postulated that ARL4C may exert an influence on the progression of cancer through the regulation of these immune-related signaling pathways." (PMID 38178862, 2023). "Therefore, univariate Cox regression analysis was conducted to examine the relationship between ARL4C expression levels and OS in various cancer types." (PMID 38178862, 2023). "Moreover, ARL4C expression has been identified in cancer cells in other reports, but in our study, ARL4C expression was identified in cancer cells as well as cancer stromal cells." (PMID 37237373, 2023). "ARL4C expression was significantly higher in cancer stromal cells than in CRC cells (P < 0.0001)." (PMID 37237373, 2023). "Further analysis of ARL4C in cancer cells of TB is necessary." (PMID 37237373, 2023). "In cancer cells, ARL4C expression was localized at the invasion front." (PMID 37237373, 2023). "Conversely, ARL4C displayed a negative association with immunosuppressive genes in certain cancer types." (PMID 38178862, 2023). "The results showed that ARL4C was differentially expressed in various cancers." (PMID 35774359, 2022). "As TGF‐β1 is identified as an important inducer of the malignant progression of cancer, we investigated whether ARL4C might participate in TGF‐β1–induced progression of GC." (PMID 33724652, 2021). "Because the perineural invasion is considered as one of the causes of the recurrence and metastasis after pancreatic resection, ARL4C expression may be correlated with the ability of cancer cell invasion." (PMID 34590580, 2021). "Emerging evidence suggests that ADP-ribosylation factor like-4c (Arl4c) may be a potential choice for cancer treatment." (PMID 34849465, 2021). "Recently, several groups investigated the role of ARL4C in different types of cancer." (PMID 32426352, 2020). "Additionally, the decrease in ARL4C expression leads to the impairment of cancer cell proliferation and migration in vitro and in vivo, as well as a reduction in expression of PI3K Catalytic subunit Delta (PI3KCD) mRNA and activity of Akt." (PMID 32426352, 2020). "However, previous ARL4C immunostaining suggests ARL4C positivity in cancer stromal cells." (PMID 37237373, 2023). "The expression level of ARL4C may play an important role in cancer development and poor prognosis." (PMID 38178862, 2023). "Thus, ARL4C would activate different downstream pathways in a cancer cell context-dependent manner." (PMID 34590580, 2021).
cancer (continued). "We identified cancer-relevant genes (ING1, ARL4C) whose expression between patients is influenced by enhancer differences in genomic copy number and germline SNPs, and HNF4α as a master trans-acting factor associated with GC enhancer heterogeneity." (PMID 34635154, 2021). "Alone this line, our finding added another path, ARL4C/JAK2/STAT5/β-catenin, as a new means for cancer cells to escape the survival inhibition by Erlotinib." (PMID 33194732, 2020). "Our data supported that the downregulation of ARL4C upregulated β-catenin via activation of JAK2/STAT5, which could help the EGFR-path-blocked cancer cells to regain their malignant behaviors." (PMID 33194732, 2020). "The results indicate that ARL4C could be a “switch” between the EGFR path and the JAK2/STAT5/β-catenin path to maintain the proliferation, migration, and invasion of cancer cells when cells are exposed to Erlotinib and EGFR path is blocked." (PMID 33194732, 2020). "Of these 4 biomarkers, ARL4C is a transcriptional factor induced by cooperative signaling of Wnt/β-catenin and EGF/Ras-MAPK signaling activation, which promotes proliferation, migration, and invasion of cancer cells." (PMID 33092599, 2020). "ARL4C expression in cancer stromal cells has not been reported by immunostaining, so ARL4C expression may be an RNA in situ phenomenon only." (PMID 37237373, 2023). "However, in cancer cells, ARL4C expression was not correlated with TB grades (r = 0.1730, P = 0.1647)." (PMID 37237373, 2023). "Of interest, although these regulatory relationships remained in the 2D culture system, we did not observe any significant effect of Arl4c on cancer cell growth, implying the existence of other regulatory mechanisms downstream of Arl4c, which require further exploration." (PMID 34849465, 2021). "Recent studies have indicated that ARL4C could be induced by EGF and promotes the motility of cancer cells by remodeling actin cytoskeleton through Arf6 activation, which might be involved in the migration, invasion, and proliferation of cancer cells." (PMID 33194732, 2020).
adenocarcinoma (4 papers, 2016 to 2026). A common cancer characterized by the presence of malignant glandular cells. "ARL4C expression is directly correlated with different histologic stages (adenocarcinoma, minimally invasive adenocarcinoma, and invasive adenocarcinoma) and is associated with a poor prognosis." (PMID 33740988, 2021).
ARL4C also shares sentences with these, for which no sentence is quoted: cholangiocarcinoma (2 papers); endocervical adenocarcinoma (2); esophageal carcinoma (2); paraganglioma (2); pheochromocytoma (2); bladder urothelial carcinoma (1); breast invasive carcinoma (1); carcinosarcoma (1); cardiovascular diseases (1); Clear Cell Renal Cell Carcinoma (1); diffuse large B-cell lymphoma (1); endometriosis (1); esophageal adenocarcinoma (1); glomerulonephritis (1); Huntington disease (1); infertile (1); kidney chromophobe (1); lung (1); lung diseases (1); lymph node metastasis (1); lymphoid neoplasm (1); non-small cell lung carcinoma (1); oral carcinoma (1); Pan (1); prostate adenocarcinoma (1); pulmonary arterial hypertension (1); rectum adenocarcinoma (1); skin cancer (1); skin cutaneous melanoma (1); squamous cell carcinoma (1).
A further 4 diseases each share a sentence with ARL4C in 1 paper.